VARS1 (valyl-tRNA synthetase 1)
Description:
Catalyzes the attachment of valine to tRNA(Val).
Synonyms: G7A; VARS; VARS2; NDMSCA
Tractability: PROTAC: ubiquitination databases record sites on it; a small molecule that binds it is known.
Target class: Enzyme; Ligase
Gene: Protein-coding gene on chromosome 6 (31,777,518 to 31,795,950, reverse strand). Ensembl gene ENSG00000204394.
Subcellular location (Human Protein Atlas): Cytosol; Endoplasmic reticulum; End piece; Mid piece; Principal piece
Pathways (Reactome):
Metabolism of proteins: Cytosolic tRNA aminoacylation
Gene Ontology:
Molecular function: protein binding; valine-tRNA ligase activity; aminoacyl-tRNA deacylase activity; aminoacyl-tRNA ligase activity; ATP binding; nucleotide binding
Biological process: tRNA aminoacylation for protein translation; valyl-tRNA aminoacylation; aminoacyl-tRNA metabolism involved in translational fidelity
Cellular component: cytosol
Genetic constraint (gnomAD): Loss-of-function variants: 92 observed, 165.03 expected, observed/expected ratio (o/e) 0.56, 90% interval 0.47 to 0.66. The upper end of that interval is the gene's LOEUF score, 0.66, which puts it in group 2 of 6, group 1 being the genes least tolerant of losing a copy. Missense variants: 1,338 observed, 1,736.9 expected, observed/expected ratio (o/e) 0.77, 90% interval 0.74 to 0.81. Synonymous variants: 595 observed, 702.26 expected, observed/expected ratio (o/e) 0.85, 90% interval 0.79 to 0.91.
Gene-disease validity (ClinGen):
ClinGen rates the evidence that VARS1 causes each of these diseases.
neurodevelopmental disorder with microcephaly, seizures, and cortical atrophy (autosomal recessive): Definitive.
Homologues: Orthologues: chimpanzee VARS1 (99% identical), macaque VARS1 (99% identical), dog VARS1 (94% identical), pig VARS1 (94% identical), mouse Vars1 (93% identical), rat Vars1 (93% identical), rabbit VARS1 (91% identical), guinea pig VARS1 (90% identical), zebrafish vars1 (66% identical), tropical clawed frog vars1 (65% identical), Drosophila melanogaster ValRS (50% identical), Caenorhabditis elegans glp-4 (44% identical). Paralogues in human: VARS2 (42% identical), IARS2 (18% identical), IARS1 (17% identical), LARS1 (14% identical), LARS2 (14% identical), MARS1 (14% identical), MARS2 (9% identical).
Diseases named in the same sentence as VARS1 in open-access papers:
VARS1 is named in the same sentence as 22 diseases in open-access papers, as found by Europe PMC text mining. Sharing a sentence is not in itself a finding about the gene and the disease. The quoted sentences say what the papers report.
melanoma (6 papers, 2020 to 2025). A malignant, usually aggressive tumor composed of atypical, neoplastic melanocytes. "VARS1 was a hub gene in the M2-like macrophage-associated WGCNA module that the DepMap portal demonstrated was necessary for melanoma growth." (PMID 36303162, 2022). "Previous studies have built an M2‐like TAM‐related prognostic model for melanoma and explored the role of VARS1 in melanoma progression and M2 macrophage polarization." (PMID 38886907, 2024). "Overexpressing VARS1 in vitro increased melanoma cell migration and invasion, while downregulating VARS1 had the opposite result." (PMID 36303162, 2022). "We hope that our research widens the current understanding of the role of M2-like TAMs in the biology of melanoma and prognosis prediction and that VARS1 can be a novel predictive biomarker of clinical outcome and immunotherapy response in melanoma." (PMID 36303162, 2022). "We established an M2-like TAM-related prognostic model for melanoma and explored the role of VARS1 in melanoma progression, M2 macrophage polarization, and the development of immunotherapy resistance." (PMID 36303162, 2022). "VARS1 overexpression promoted M2-like macrophage polarization and melanoma cell migration and invasion in vitro, while knockdown of VARS1 decreased melanoma cell migration and invasion." (PMID 36303162, 2022). "We also examined whether VARS1 played an important role in melanoma progression and constructed VARS1-overexpressing and VARS1 knockdown A375 and SK-MEL-28 cell lines." (PMID 36303162, 2022). "The role of VARS1 in melanoma remains unclear, which prompted our exploration of the function of VARS1 as a potential prognostic biomarker in melanoma." (PMID 36303162, 2022). "In addition, further animal experiments are necessary for exploring the functional role of VARS1 in melanoma, which can help provide more robust clues to guide clinical application." (PMID 36303162, 2022). "Interestingly, only VARS1 was identified after intersection between these hub genes and the melanoma cell growth-related genes in the DepMap database, indicating that VARS1 was associated with M2-like TAM polarization and melanoma tumor cell growth." (PMID 36303162, 2022). "Subsequently, VARS1 was characterized as the hub gene of the module most associated with M2-like TAM infiltration, which suggested that VARS1 is linked to TAM polarization and could be defined as a new potential target in melanoma progression." (PMID 36303162, 2022). "Furthermore, we explored which cell type mainly expressed VARS1 in melanoma." (PMID 36303162, 2022). "Nevertheless, the role of VARS1 in melanoma remains unclear." (PMID 36303162, 2022). "Furthermore, a search of the Human Protein Atlas (HPA) database showed that VARS1 expression was increased in primary melanoma compared to normal skin tissue, and further increased in metastatic melanoma." (PMID 36303162, 2022).
microcephaly (5 papers, 2019 to 2025). A congenital or acquired developmental disorder in which the circumference of the head is smaller than normal for the person's age and sex. "The fact that the previously reported VARS1 mutations were associated with microcephaly and epilepsy made us focus on the VARS1 variant." (PMID 37529793, 2022). "Through whole exome sequencing (WES), we detected a novel homozygous VARS1 variant i.e. p.T1068M, in an affected individual who was experiencing microcephaly, developmental delay, and drug-resistant seizures." (PMID 37529793, 2022). "Another example of ARS1-associated disorders, in which an impaired protein synthesis as the causative disease mechanism can be questioned is VARS1 causing developmental delay with microcephaly." (PMID 34536092, 2021). "As in the previously reported VARS1 mutations, the affected individual harboring p.T1068M was experiencing a neurodevelopmental disorder with intractable seizures, psychomotor retardation, and microcephaly." (PMID 37529793, 2022).
leukodystrophy (1 paper, 2024). Leukodystrophies are a group of rare, progressive, metabolic, genetic diseases that affect the brain, spinal cord and often the peripheral nerves. "Pathogenic variants of genes encoding aminoacyl-tRNA synthetases (ARS) have been linked to a number of neurodegenerative diseases, including hypomyelinating leukodystrophies (e.g., EPRS1, VARS1, DARS1 and RARS1)." (PMID 39062571, 2024). "In the last few years, our group has identified and validated eight genes causative for leukodystrophy, including POLR3A, POLR3B, POLR1C, POLR3D, EPRS1, VARS1, and ABHD16A." (PMID 39062571, 2024).
cancer (8 papers, 2016 to 2024). A tumor composed of atypical neoplastic, often pleomorphic cells that invade other tissues. "GSEA indicated that many immune-related pathways, such as the T cell-mediated cytotoxicity pathway, were enriched in the patients with high VARS1 expression in 70% of cancer types." (PMID 36303162, 2022). "High VARS1 expression was correlated with poorer survival in six cancer types, including KICH (hazard ratio [HR] = 2.80), MESO (HR = 1.74), SKCM (HR = 1.32), SARC (HR = 2.25), LAML (HR = 1.69), and CESC (HR = 1.49) and with better survival in READ (HR = 0.47)." (PMID 36303162, 2022). "In addition, our analysis of the Pan-TCGA datasets supported the idea that high VARS1 expression was correlated with poor CD8 T cell infiltration in most cancers." (PMID 36303162, 2022). "Furthermore, pan-cancer analysis revealed that VARS1 correlated negatively with CD8 T cell infiltration in most cancers and demonstrated unfavorable prognostic value in several cancers." (PMID 36303162, 2022). "TARS1, VARS1, CARS2, DARS2, and YARS2 are associated with unfavorable outcomes in two cancer types." (PMID 33266490, 2020). "Eight proteins (A4GALT, ASIP, CTSF, MARE1, PDXK, SEM4A, PLAUR, VARS1) were observed to have evidence of multi-trait colocalization between the index protein, intermediate phenotypes, and the index cancer endpoint, which may serve to elucidate aetiological pathways to cancer risk." (PMID 38684708, 2024). "The heatmap showed that VARS1 gene expression and CD8 T cell infiltration were inversely correlated in most cancers." (PMID 36303162, 2022). "Pan-cancer analysis demonstrated that VARS1 expression negatively correlated with CD8 T cell infiltration and the immune response-related pathways in most cancers." (PMID 36303162, 2022).
tumor (3 papers, 2019 to 2025). "Moreover, our results showed that VARS1 was mainly expressed by tumor cells and that high VARS1 expression was significantly associated with poor OS and the metastasis-related pathway in TCGA-SKCM dataset." (PMID 36303162, 2022). "Our in vitro experiments demonstrated that VARS1 upregulated TGF-β1 expression in tumor cells and the M2 macrophage marker CD206." (PMID 36303162, 2022). "GSVA of the KEGG pathways revealed that the immune-related pathways, such as the T cell receptor pathway, were enriched in patients with low VARS1 expression, while tumor growth pathways such as the cell cycle pathway and the mTOR pathway were enriched in patients with high VARS1 expression." (PMID 36303162, 2022). "VARS1 overexpression promoted M2 macrophage polarization and increased TGF-β1 concentrations in tumor cell supernatant in vitro." (PMID 36303162, 2022). "The result of single-cell RNA-seq of the GSE115978 dataset demonstrated that VARS1 was expressed predominantly in tumor cells but not in stromal and immune cells." (PMID 36303162, 2022).
VARS1 also shares sentences with these, for which no sentence is quoted: breast carcinoma (2 papers); colon cancer (2); developmental delay (2); epilepsy (2); neurodevelopmental disorder (2); cervical cancer (1); cholera (1); cortical atrophy (1); diarrheal disease (1); Epileptic encephalopathy (1); infection (1); iridocyclitis (1); liver cancer (1); lung carcinoma (1); metastatic melanoma (1); Parkinson’s disease 7 (1); X-linked disease (1).